MMP9 (matrix metallopeptidase 9)
Diseases named in the same sentence as MMP9 in open-access papers (continued):
Sharing a sentence is not in itself a finding about the gene and the disease.
tumor (continued). "Our data indicated that combination of the clinical risk scores (TNM stage, histologic type, and tumor diameter), TIMP-2 or MMP-9 or TIMP-2 plus MMP-9 expression predicted prognosis of CRC." (PMID 31293204, 2019). "We found that expression of Ki-67, a cell proliferation marker, and MMP-9, a cell metastatic marker in xenograft tumor tissue samples were inhibited in LV-sh-UCA1, in contrast with LV-sh-con." (PMID 31798345, 2019). "Conditioned medium from TAMs significantly promotes cell migration and invasion in various types of human tumor cell lines, while blocking uPA and MMP-9 can inhibit TAM-induced invasion." (PMID 31629410, 2019). "First, we used the Repository of Molecular Brain Neoplasia Data (REMBRANDT) dataset to compare mRNA expression of MMP-2 and MMP-9 in non-tumor control and GBM samples." (PMID 31590360, 2019). "The inhibition of tumor cell migration observed in wound-healing and transwell assay was found to be due to MMP-9 suppression that is controlled by AKT/mTOR axis." (PMID 31052558, 2019). "All these results suggest the contributory role of MMP-9 in oral carcinogenesis, tumor invasion and metastasis." (PMID 31831717, 2019). "Namely, MDSCs can increase production of MMP9 (involved in tumor angiogenesis promotion) or enhance tumor cell invasion and migration through the TGFβ pathway." (PMID 30548868, 2019). "In the TME, MDSCs, by production of VEGF, FGF2, Bv8, and matrix metalloprotease (MMP) 9 (MMP9), can trigger and sustain tumor angiogenesis." (PMID 31057536, 2019). "MMP-9 (gelatinase B) is related to tumor invasion and metastasis by its special capacity to degrade type IV collagen and to induce angiogenesis." (PMID 31086100, 2019). "Increased activation of MMP2 and MMP9 is mediated by the levels of IL-8, which can promote the invasive capability of a tumor." (PMID 30664713, 2019). "It was concluded that the increase in MMP-2, TIMP-1 in tumor, and MMP-9 in stroma were characterized by a decrease in the odds ratio for 5-year survival." (PMID 31223594, 2019). "Inhibition of the expression of MMP9 with amino-biphosphonate in tumor-bearing mice decreased the number of MDSCs in the spleen and tumor tissues and resulted in a significant delay in the growth of spontaneous NeuT tumors in transgenic BALB/c mice." (PMID 31225500, 2019). "On the other hand, patients with tumor size >1 cm had a higher serum MMP-9 level than those tumor size ≤1 cm (median 89.34 ng/ml, IQR 69.98‒116.99 vs. median 74.91 ng/ml, IQR 61.91‒109.03; P=0.013)." (PMID 33817161, 2019). "Thirdly, MMP-9 promotes tumor progression by cleaving a variety of substrates, including growth factor precursors, growth factor binding proteins, receptor tyrosine kinases, cell adhesion molecules, and other proteinases." (PMID 33817161, 2019). "These EVs have been shown to activate dendritic cells and induce secretion of interleukin-6, which promotes tumor invasion by increasing MMP-9 metalloproteinase expression." (PMID 30925923, 2019). "The expression of genes related to CRC (i.e., SDF‐1, CRCX 4, VEGF and MMP‐9) at the mRNA and protein levels was detected in the tumor tissues of mice." (PMID 31665829, 2019). "CH treatment significantly (p < 0.05) reduced the protein expression of VEGF and MMP9 in the tumour of the mice compared to the untreated 4T1-challenged mice." (PMID 30814922, 2019). "CAFs maintain the stem cell-like properties of HCC cells by secreting IL-6 and promote tumor invasion and metastasis by secreting matrix metalloproteinase-9 (MMP-9)." (PMID 31142326, 2019). "CD11b+Gr1+ MDSCs cells directly contribute to tumor angiogenesis by producing MMP9 or acquiring endothelial cell properties in TME." (PMID 31057536, 2019). "Given that MMP-9 can degrade components of the basement membrane, it is considered to be involved in processes requiring basement membrane disruption, such as tumor invasion and tissue infiltration of T lymphocytes." (PMID 33817161, 2019).
tumor (continued). "Increased MMP (e.g., MMP-2, MMP-7 and MMP-9) expression occurs frequently upon Wnt stimulation of tumour cell invasion." (PMID 31718047, 2019). "MMP-9 can degrade collagen IV in tumor tissue, promoting the vascularization and infiltration of EC." (PMID 31824776, 2019). "Upon activation, neutrophils form NETs, which have been shown to promote extravasation by tumor cells sequestration and MMP-9-mediated degradation of ECM." (PMID 30927923, 2019). "It seems that higher expression values of MMP-9 in tumor and stroma for the N1+N2 stage in comparison to the N3 stage are the results of a constant high expression level of TIMP-1, which inhibits the release of metalloproteinase-9." (PMID 31223594, 2019). "Among the others, CCL2, CCL3, and CCL5 contribute to tumor vascularization and metastasis and also stimulate MMP9 secretion by monocytes, which strongly favors tumor cell extravasation." (PMID 31484464, 2019). "All non-tumoral breast tissues showed low expression/activity of both ENO1 and MMP-2 and MMP-9, whereas higher expression/activity was observed in the paired tumour samples." (PMID 31416219, 2019). "We found that the expression and enzyme activity levels of MMP-2 and MMP-9 were decreased in mouse tumor tissues after LOX inhibition." (PMID 31777578, 2019). "Third, MMPs, especially MMP2 and MMP9, that degrade constituents of the extracellular matrix to disrupt the physiological barrier were found to participate in tumour metastasis." (PMID 31423109, 2019). "Proteomics analysis of tumor-associated EVs has shown that EVs release a number of proteins such as SERPINA1, SERPINF2, and MMP9, the up-regulation of which play a significant role in ECM remodeling, vascular leakiness, and invasiveness." (PMID 30925923, 2019). "The PI3K/AKT axis plays a principal role in metastasis and tumor invasion through activation of NFκB-mediated MMP-9." (PMID 31068208, 2019). "In the multivariate analysis, the factors which influence 3-year survival included the changes in MMP-9 expression in the tumor and stroma, as well as TIMP-1 in the stroma." (PMID 31223594, 2019). "In colorectal cancer, miR-497 targets VEGF-A, leading to blockade of the VEGF-A/ERK/MMP-9 signaling pathway and the attenuation of tumor angiogenesis, invasion, and metastasis." (PMID 31757094, 2019). "In order to evaluate the mechanism underlying their inhibitory action on migration and invasion, we measured the activities of MMP-2 and MMP-9 involved in tumor cell migration and invasion by gelatin zymography." (PMID 31109130, 2019). "Anti‐MMP9 antibody monotherapy resulted in more gene expression changes in the mouse stroma compared to the human tumour compartment." (PMID 30941918, 2019). "Using zymography, we analyzed the MMP2 and MMP9 content in serum-free medium collected from tumor cells 12 h after the removal of THP1 cells at each co-cultivation step." (PMID 31861801, 2019). "This suggests that LOX can upregulate the expression and enzyme activity of MMP-2 and MMP-9, which verified our results in human tumor tissues." (PMID 31777578, 2019). "The authors observed that DANCR sponged miR-34c and miR-613, two miRNAs with tumor suppression function that target matrix metallopeptidase 9 (MMP9), an important protein for the breakdown of ECM." (PMID 31798638, 2019). "More importantly, after silencing LNMAT1 expression in MM cells with shRNAs (P < 0.05), the mRNA expression levels of MMP-2, MMP-9, and N-cadherin, which are markers of tumor invasion-metastasis cascade, were found to be downregulated by qRT-PCR." (PMID 31334110, 2019). "MMP2 and MMP9 were members of metal matrix protease family, which was closely related to tumor migration." (PMID 31384174, 2019). "Overexpression of MMP-9 and other MMPs results in the suppression of T-lymphocyte proliferation and response against tumor affected cells, since they release TGF-β, a noteworthy silencer of T-lymphocyte response against malignant cells." (PMID 31662772, 2019).
tumor (continued). "We demonstrated that high MMP-9 expression in CRC tumor tissues was significantly related to age, pathological classification, depth of invasion, lymph node metastasis, distant metastasis, and TNM stage." (PMID 31293204, 2019). "MMP-2 and MMP-9 expression is elevated in malignant tumors and largely contribute to the ability of tumor cells to metastasize, as they degrade collagen type IV, which is the main component of the basement membrane." (PMID 31554180, 2019). "Several studies suggested that overexpression of MMP-2 and MMP-9, upon their role in OPN-induced tumor invasion, is associated with an aggressive phenotype of cancers." (PMID 31934533, 2019). "At molecular level, the expression of MMP-2 and MMP-9 in tumor tissues was also reduced by DANCR inhibition." (PMID 31827393, 2019). "It is also noteworthy to mention that, in addition to its role in migration, invasion and metastasis, MMP-9 is known to play a crucial role angiogenesis as well as tumor formation." (PMID 31456939, 2019). "Their conclusion was that an elevated MMP7 and MMP9 play a role in the release of circulating tumor cells into the peripheral blood." (PMID 31191742, 2019). "Despite the lack of significance, a higher expression of MMP-2 in stroma and tumor was observed in patients who survived in 3 and 5 years, and an inverse correlation for the expression of MMP-9, which was confirmed based on the literature." (PMID 31223594, 2019). "Previous studies have reported that BASR-CHMs promote angiogenesis by upregulating vascular endothelial growth factor (VEGF) gene in the ischemic model and inhibit angiogenesis mainly by downregulating VEGF and decreasing MMP9 expression in tumor tissues." (PMID 31607901, 2019). "MMPs, such as MMP9, are important in destroying the extracellular matrix barrier via the degradation of type IV collagens and assisting the tumor cell invasion and metastasis." (PMID 30041514, 2019). "MMP-2 and MMP-9 are matrix metalloproteases expressed in tumor cells, which degrade the extracellular matrix (ECM) type IV collagen of the basement membrane during cancer invasion and metastasis." (PMID 31293975, 2019). "In tumor bearing mice, MMP-9 promotes HCC, lung and pancreatic cancer angiogenesis by promoting neutrophil recruitment." (PMID 31799175, 2019). "To characterize the features of tumor xenograft model, we performed IHC staining for cell proliferation marker PCNA, microvessel density marker CD34 and metastasis-associated marker MMP-9 in xenograft tissues." (PMID 30791942, 2019). "In a pre-clinical study, an anti-MMP9 monoclonal antibody GS-5745 successfully inhibited tumor growth and reduced tumor metastasis in mice bearing colorectal tumors." (PMID 31106200, 2019). "Only the introduction of the MMP-9 variable or expression difference for metalloproteinase in tumor and stroma allows for the assessment of prognoses concerning the survival of the patient." (PMID 31223594, 2019). "Taken together, these results suggest that TNF-α production by TRIM59-/--M2 macrophages promotes the expression of MMP-9 and Madcam1 in B16-F0 and B16-F10 tumor cells, enhancing their metastatic potential." (PMID 31600735, 2019). "The role of gelatinases in the development of diseases has been shown through the participation of MMP-2 and MMP-9 in tumor invasion and progression." (PMID 31037923, 2019). "Inhibition of active MMP9 early during tumorigenesis suppresses tumor cell migration, invasion, and colony formation and tilts the balance towards anti-tumor immunity by activating CD8+ T cells." (PMID 31727800, 2019). "To illustrate the anti-metastatic mechanism of YFTL, we measured E-cadherin, N-cadherin, Vimentin, MMP-2, and MMP-9 expression in tumor and lung tissues of Lewis lung cancer mice by immunohistochemistry and Western blot analysis." (PMID 30781674, 2019).
tumor (continued). "Among MMPs, MMP-2 and MMP-9 are two important enzymes, which are involved in the remodeling of extracellular matrix and are key mediators of invasion, metastasis, and tumor angiogenesis and facilitate VM formation." (PMID 30723742, 2019). "On the contrary, inhibition of MMP-9 leads to attenuated tumor cell growth and decreased invasive and migratory abilities of cancer cells." (PMID 33817161, 2019). "The relationship between LOX and MMP-2 and MMP-9 in tumorigenesis and tumor progression are still unclear." (PMID 31777578, 2019). "A study conducted in multiple tumor cell lines showed that the expression of MMP-9 is regulated by the FAK-ERK1/2-Akt pathway, through the regulation of p65 and c-Fos." (PMID 31554180, 2019). "Isoginkgetin was reported as a general inhibitor of pre-mRNA splicing and can inhibit HT1080 tumor cell invasion by regulating PI3K/AKT1-dependent matrix metalloproteinase (MMP)-9 expression." (PMID 30995808, 2019). "We deciphered the actions of FT also on the constitutive levels of COX-2 and MMP-9 proteins that can regulate the invasive ability of tumor cells." (PMID 31284669, 2019). "In turn, the increase of MMP-2 expression in stroma and its decrease in tumor occurs with the increasing degrees of regional staging; however, MMP-9 expression decreases in both locations with the increase of the N feature." (PMID 31223594, 2019). "The changes in dynamics with increasing N stage indicate a decrease in MMP-9 expression both in tumor and stroma with a simultaneous increase of TIMP-1 expression." (PMID 31223594, 2019). "There are 24 MMPs in mammals, of which MMP2 and MMP9 are found to be overexpressed in many cancer types and promote tumor progression and metastasis." (PMID 31106200, 2019). "Dishevelled was positively correlated with the proliferation index Ki‐67, tumour invasion index MMP‐9 and β‐catenin, and transferred to the nucleus which indicated its involvement in the proliferation and invasion processes." (PMID 30468298, 2019). "MMP9 degrading collagen IV, which is a major component of basement membranes, facilitates tumor cells invasion (Malik, Lelkes & Cukierman, 2015)." (PMID 31367490, 2019). "In various types of tumors, MMP-9 expression is primarily implicated in metastatic phenotypes by acting upon the ECM components thereby altering adhesive capability and in promoting tumor vascularization." (PMID 31052558, 2019). "CD44 provides a surface docking station for active proteolytic MMP9; this specific localization at the cell membrane is required for MMP9’s ability to promote tumor invasion." (PMID 31810195, 2019). "In this study, we aim to investigate the associations of MMP‐9 with the activation of transforming growth factor beta (TGF‐β)/SMAD signalling and the malignancy of breast malignant tumour cells." (PMID 31264317, 2019). "MAPK and Akt have been shown to be involved in MMP-9 induction in various tumor types and migratory cell phenotypes." (PMID 31817413, 2019). "A similar expression was observed in relation to MMP-9 in tumor, where its expression was significantly higher in patients without metastases (P=0.0168)." (PMID 31223594, 2019). "The hnRNPR-positive cells or MMP9 positive areas in shhnRNPR tumor were remarkably reduced than those in the control tumors." (PMID 31527303, 2019). "The protein expression levels of the tumor invasion and migration-related proteins matrix metalloproteinase 9 (MMP9) and MMP2 were also reduced by Akt inhibition." (PMID 30850586, 2019). "inhibited the expressions of p-Stat3 and MMP-9, which are generally acknowledged to be correlated positively with tumor metastasis." (PMID 31649548, 2019). "Further, it was shown that inhibition of either tumor, or stroma-derived MMP-9, was sufficient to reduce primary tumor growth." (PMID 31216704, 2019). "Akt activation has been shown to induce EMT and MMP9 activity and to promote tumor invasiveness and metastasis." (PMID 30850586, 2019).
tumor (continued). "In fact, MMP-9 is induced under conditions that require tissue remodeling (including tumor invasion)." (PMID 31416219, 2019). "In recent years, proteins that decorate NETs, such as NE and matrix metalloproteinase-9 (MMP-9) have been investigated for their role in promoting local tumor growth." (PMID 31416173, 2019). "Matrix metalloproteinase 9 (MMP-9) and gelatinase B, modulates cell growth, invasion, and metastasis leading to tumor progression." (PMID 31238539, 2019). "The results indicated that both TGFβ1 receptor and Smad2 were involved in the process that MSCs facilitated the expression of FAPa and MMP9 in VX2 tumor tissue." (PMID 31528217, 2019). "The downregulation of phospho-AKT/phospho-mTOR after Salmonella treatment in both B16F10 and LL2 cells resulted in a decrease of MMP-9 expression which was reversed in tumor cells transfected with constitutively active AKT." (PMID 31052558, 2019). "NF-κB, AP-1, and Sp-1 are transcription factors that regulate MMP-9 expression involved in the migration and invasion of tumor cells." (PMID 31391858, 2019). "And the expression of IL‐6, IL‐1β, TNF‐α and MMP9 in tumor samples were also markedly up‐regulated compared with non‐tumor parts." (PMID 30903649, 2019). "MMP-2 and MMP-9 are the most important factors in the MMP family in promoting tumor invasion and metastasis." (PMID 30622441, 2019). "In order to confirm the relationship between LOX and MMP-2 and MMP-9 in tumorigenesis and tumor progression, we studied LOX, MMP-2, and MMP-9 in human tumor tissues, animal models, and in vitro cell culture." (PMID 31777578, 2019). "MMP9 is required for the degradation of the extracellular matrix, which is a prerequisite for tumour invasion and positively correlates with tumour metastasis." (PMID 31569419, 2019). "To assess the effects of MMP-9 and Madcam1 deletion on tumor growth in vivo, we subcutaneously injected B16-F10 cells transfected with shRNA-MMP-9, shRNA-Madcam1, or scrambled control-shRNA into WT or TRIM59-CKO mice." (PMID 31600735, 2019). "Methylation analysis of the Cdh1, Cdh2, Mmp9, Mki67, Gfap, Gap43, Robo2, and Slit2 genes from tumor samples demonstrated that all of them were methylated in their promoter regions unlike those from normal tissues." (PMID 31921388, 2019). "The stromal cells overexpress MMP9 in inflammatory disease, albeit with a greater expression in tumor cells." (PMID 31191742, 2019). "In the tumor microenvironment, elevated levels of MMPs such as MMP-9 were able to induce epithelial-mesenchymal-transition (EMT), whereas EMT itself promotes MMP-9 secretion that facilitates cell invasion and metastasis." (PMID 30728391, 2019). "In fact, the inhibition of MMP-9 and αVβ5-integrin interaction results in a reduced angiogenesis and tumor invasion." (PMID 31086100, 2019). "In tumor cells, MSE is positively correlated with HIF1α, MMP2 and MMP9 expression and thus can reflect the status of the tumor microenvironment." (PMID 31266540, 2019). "In the case of MMP-9, statistically significant lower expression values were observed in stromal tissue (P=0.0445) in comparison to tumor tissue." (PMID 31223594, 2019). "The aim of this study is to examine the expression level of 4 tumor-promoting biomarkers including MMP9, CK20, CK19, and uPA in the peripheral blood and the prognosis of patients with ESCC." (PMID 30817615, 2019). "Here we demonstrate that miR-34a exerted tumor-suppressive effects in HGSC by regulating the IL-6R/STAT3 signaling pathway and the associated expression of Snail, MMP9, CDK4, and survivin." (PMID 31448054, 2019). "After LOX inhibition, we analyzed the effects on protein expression and enzyme activity of MMP-2 and MMP-9 in tumor tissues from the nude mouse model." (PMID 31777578, 2019). "In the present study, we recognized medium and strong expressions of MMP-9 in most tumor stroma cells and in the inflammatory cells infiltrating this compartment." (PMID 31143300, 2019).